RELA (RELA proto-oncogene, NF-kB subunit)
Diseases named in the same sentence as RELA in open-access papers (continued):
Sharing a sentence is not in itself a finding about the gene and the disease.
breast tumors (12 papers, 2007 to 2024). "Furthermore, the breast tumor subtypes exhibit different forms of NF-κB activation, some associated with enhanced p50/RelA DNA binding, some with enhanced p50 or p52 DNA binding activity, some with enhanced c-Rel expression." (PMID 32349210, 2020). "Activated NF-κB (p50/RelA) was detected predominantly in ER-negative vs. ER-positive breast tumors and mostly in ER-negative and ErbB2-positive tumors (86%)." (PMID 32349210, 2020). "To evaluate the correlation between proliferation and RelA, we reanalyzed a cohort of breast tumors where the same RelA antibody was used for staining and Ki67 staining was available (Croatia cohort;)." (PMID 26460486, 2015). "Membership in the four RelA-defined groups was observed in all biomarker-defined subtypes of breast tumors (Boston cohort)." (PMID 26460486, 2015). "A similar mechanism may be operating in ER+/HER2- breast tumors that express high levels of RelA resulting in diminished proliferation." (PMID 26460486, 2015). "We speculated that lower proliferation rates in ER+/HER2- breast tumors with high levels of RelA may be due to diminished CDK4 levels." (PMID 26460486, 2015). "Our results from mechanistic studies in HMEC, gene expression analysis of ER+/HER2- tumors from the TCGA cohort and analysis of ER+/HER2- breast tumors by IHC implicate basal activity of RelA in suppressing proliferation through upregulation of IRF1 and downregulation of CDK4." (PMID 26460486, 2015). "We next tested whether low ING4 expression correlated with NF-κB activation in breast tumors by staining the TMAs with an antibody against the p65/RelA subunit phosphorylated at the amino acid residue serine 276 (p-p65/RelA), an activated form of NF-κB." (PMID 23056468, 2012). "We found that low ING4 expression correlated with high levels of phosphorylated p65/RelA (p-p65/RelA), an activated form of NF-κB, in breast tumors, suggesting that down-regulation of ING4 may foster NF-κB activation in breast cancer." (PMID 23056468, 2012). "Interestingly, IOA-289 decreased RELA expression in breast tumors." (PMID 38201482, 2023). "Therefore we hypothesized that ER+ tumors with high levels of RelA are likely to be restrained by the tumor-suppressive RelA-IRF1-CDK4 axis while RelA expression levels may have little impact on the other subtypes of breast tumors." (PMID 26460486, 2015). "Finally, using a semi-quantitative IHC assay to assess the intracellular distribution and relative levels of RelA in breast tumor sections and Ki67 as a marker for proliferation, we confirmed the negative correlation between elevated RelA and proliferation in ER+/HER2- tumors." (PMID 26460486, 2015). "CDK4 levels in ER+/HER2- breast tumors may similarly be negatively regulated by RelA." (PMID 26460486, 2015). "First, we explored cancer databases and established that TNF-α, RELA and ATX in breast tumors showed positive correlations in patients." (PMID 38201482, 2023). "Intriguingly, p50/RelA heterodimer was documented to be related in nearly 86% of estrogen receptor (ER)-negative and Her2/ErbB2-positive breast tumors." (PMID 36422540, 2022). "Proliferation rates in the other subtypes of breast tumors were fairly similar and independent of RelA levels." (PMID 26460486, 2015). "Using immuno-histochemical analysis of breast tumors, we confirm the negative correlation between RelA levels and proliferation rate in ER+/HER2- breast tumors." (PMID 26460486, 2015). "The seemingly contradicting data in normal mesodermal tissues and breast tumor cell lines may indicate there are additional players modifying the functional relationships between TWIST1 and RELA during different processes in development." (PMID 22891766, 2012).
leukemia (12 papers, 2008 to 2025). A malignant (clonal) hematologic disorder, involving hematopoietic stem cells and characterized by the presence of primitive or atypical myeloid or lymphoid cells in the bone marrow and the blood. "In MLL-fused leukemia cells, the RELA-p50 complex binds to MLL1 and induces trimethylation of histone H3K4 residues in the promoter regions of HOXA9 and MEIS1." (PMID 36362853, 2022). "For the human protein RelA, also known as the p65 subunit of NFkappaB, a transcription factor with diverse functions including a role in leukaemia, inflammation and cancer, here is a good workflow that generates a nice schematic of the protein showing domains and phosphorylation sites." (PMID 30210791, 2018). "Interestingly, the NFkB family of proteins RelA as well as c-Rel were reported to enhance luciferase activity in an EZH2 reporter system, and c-Rel regulated the induction of EZH2 gene expression in activated primary murine lymphocytes and human leukemia cell lines." (PMID 29619032, 2018). "TEL-JAK2 leukemic cells displayed NF-κB activity (p50, p52, RelA, and RelB), suggesting that, in addition to a noncell-autonomous role, NF-κB activation may also contribute cell-autonomously to TEL-JAK2 leukemia development or maintenance." (PMID 18596915, 2008).
lymphoma (12 papers, 2016 to 2025). A malignant (clonal) proliferation of B- lymphocytes or T- lymphocytes which involves the lymph nodes, bone marrow and/or extranodal sites. "RNASeq and proteomic analysis revealed that the RelA T505A mutation has a major effect on the transcriptome and proteome of in Eμ-Myc/RelaT505A lymphomas." (PMID 36240065, 2022). "The main focus of this report is how the RelA T505A mutation leads to a disruption of the DNA replication response in Eμ-Myc lymphomas and insights into this came from investigating the response to treatment with the CHK1i CCT244747." (PMID 36240065, 2022). "The difference in the (phospho)proteome response to inhibitor treatment implied that the RelA T505A mutation was inducing a change or defect in ATR/CHK1 signalling in response to DNA replication stress in Eμ-Myc lymphoma cells." (PMID 36240065, 2022). "The researchers found that Eμ-Myc lymphomas containing a RelA 505A mutation have decreased expression at the mRNA level of Claspin, an important protein that promotes Chk1 activity following replication stress." (PMID 36416754, 2022). "In contrast, when NF-κB is mutated with either the cRel−/− or RelA 505A, these lymphomas are resistant to Chk1 inhibitor." (PMID 36416754, 2022). "Firstly, as we show in this paper, the RelA T505A lymphomas do respond to CCT244747, albeit in a different manner to the WT cells." (PMID 36240065, 2022). "In our parallel report examining up-regulated compensatory bypass pathways in CCT244747 resistant Eμ-Myc lymphomas we examine in more detail the up-regulated mRNAs in RelA T505A cells." (PMID 36240065, 2022). "Subsequent examination of ATR/CHK1 signalling components revealed loss of expression of the ATR/CHK1 adaptor protein Claspin in RelA T505A Eμ-Myc lymphomas." (PMID 36240065, 2022). "Total protein and phosphopeptide proteomic analysis revealed that the response of RelA T505A Eμ-Myc lymphomas to a single acute dose of CCT244747 in vivo, was both reduced and different from WT cells." (PMID 36240065, 2022). "Regardless, it is, therefore, likely that other factors can contribute to the CCT244747 resistance we see in RelA T505A lymphoma cells." (PMID 36240065, 2022). "We, therefore, conclude that the nature of this CCT244747 response is profoundly different between these two systems, with the changes in RelA T505A lymphoma cells being both smaller in number and different from those in WT lymphoma cells." (PMID 36240065, 2022). "As an example, a small molecule c-REL inhibitor showed activity against human lymphoma cells in a xenograft model (although, at least in mice, the drug also targets the RELA subunit)." (PMID 36289712, 2022). "This revealed that the RelA T505A Eμ-Myc lymphoma cells response to CHK1 inhibition is different from WT cells." (PMID 36240065, 2022). "Conversely only 66/297 of the proteins with phosphopeptide changes unique to WT cells had altered protein expression between WT and RelA T505A lymphomas." (PMID 36240065, 2022). "Of the mRNAs whose expression was significantly changed in Eμ-Myc/RelaT505A lymphomas, 19% (218/1139) were identified as potential direct RelA targets." (PMID 36240065, 2022). "When these CCT244747-induced phosphopeptide and protein differences between the WT Eμ-Myc and Eμ-Myc/RelaT505A cells were analysed in more detail, we observed that less than half were common between WT and RelA T505A lymphoma cells." (PMID 36240065, 2022). "Only 137/380 proteins with phosphopeptide differences between WT and RelA T505A lymphomas also displayed altered protein expression." (PMID 36240065, 2022). "By western blot we also see reduced Claspin protein levels in reimplanted RelA T505A lymphoma extracts." (PMID 36240065, 2022). "Despite these remaining uncertainties, this report reveals the major regulatory role that the RelA T505 phosphosite has as a regulator of the DNA replication stress response in an in vivo model of MYC driven lymphoma." (PMID 36240065, 2022).
lymphoma (continued). "Only 37/135 of the proteins with phosphopeptide changes unique to RelA T505A cells had altered protein expression between WT and RelA T505A lymphomas." (PMID 36240065, 2022). "Further analysis of some the intrinsic differences between RelA T505A and WT Eμ-Myc lymphoma cells have been performed elsewhere." (PMID 36240065, 2022). "This indicates that in contrast with our observations with Eμ-Myc/cRel−/− lymphoma cells, RelA T505A cells only partially mimic WT cells that have been treated with CCT244747." (PMID 36240065, 2022). "BRD4 also binds acetylated RELA (NFkB-p65) and is essential for NFkB transcriptional activity, necessary for survival of lymphoma cells." (PMID 33654205, 2021). "The RNA Seq analysis revealed that the RelA T505A mutation has a widespread and significant effect on RNA expression in Eμ-Myc lymphomas without CHK1i treatment, with 1139 transcripts showing significant (adjP < 0.05) differences." (PMID 36240065, 2022). "Secondly, in our parallel paper, where we investigate the compensatory bypass pathways that become activated in c-Rel null and Eμ-Myc/RelaT505A lymphomas, we show that the RelA T505A lymphomas have increased sensitivity to drugs targeting the PI3K and PAK2 kinases." (PMID 36240065, 2022). "Strikingly, comparatively few significant changes relative to WT cells were seen on the total and phosphoproteomes following acute CCT244747 treatment of RelA T505A Eμ-Myc lymphomas, with only 157 proteins and 315 phosphopeptides being differentially regulated (P ≤ 0.05)." (PMID 36240065, 2022). "Moreover, and in contrast with wild-type (WT) Eμ-Myc lymphomas, RelA T505A Eμ-Myc lymphomas are resistant to treatment with the CHK1 inhibitor CCT244747." (PMID 36240065, 2022). "These phosphorylation differences could not be completely explained by the changes in the total proteome between WT and RelA T505A lymphoma cells." (PMID 36240065, 2022). "Therefore, while RelA T505A lymphoma cells do respond to CCT244747 treatment, they do so in a profoundly different way to wild-type cells." (PMID 36240065, 2022). "To investigate whether expression of components of the ATR/CHK1 pathway itself were disrupted in RelA T505A cells, we performed qPCR analysis using RNA extracted from primary Eμ-Myc lymphomas." (PMID 36240065, 2022). "Therefore, a reduction in Claspin protein levels can account, at least in part, for the CCT244747 resistance we observe in reimplanted RelA T505A Eμ-Myc lymphomas." (PMID 36240065, 2022). "This experiment, originally performed before our RNA Seq and proteomic analysis of reimplanted Eμ-Myc lymphomas was completed, revealed lower levels of Claspin mRNA and protein expression in primary RelA T505A Eμ-Myc lymphomas, while ATR, CHK1, ATRIP, RAD17 and TOPBP1 were unaffected." (PMID 36240065, 2022). "In addition to its physiological roles in PB/PC formation, nuclear RELA has been detected across a variety of B-cell malignancies and NF-κB activation is required for the survival of several lymphomas, including ABC-DLBCL1,2." (PMID 32753663, 2020). "Interestingly, in Eμ-Myc mice RelA regulation of Bach2 was only seen in the 'end-stage' lymphomas, suggesting that c-Rel is the primary driver of Bach2 expression." (PMID 26522720, 2016). "In addition, we did select RelA T505A lymphomas that had appropriate lymph node homing characteristics and this might have also influenced the data generated." (PMID 36240065, 2022). "Moreover, consistent with RelA T505 phosphorylation being a regulator of the response to DNA replication stress, we observed significantly higher levels of γH2AX, a marker of DNA damage and genomic instability in Eμ-Myc/RelaT505A lymphomas." (PMID 36240065, 2022). "Our results highlight RELA, ETS1, NFATC1, and ITGB2 as central players in the pathogenesis of various diseases, including RA, lymphoma, asthma, acute myelocytic leukemia, and leukemogenesis." (PMID 40839671, 2025).
lymphoma (continued). "In T lymphoma cell lines, TLE5 interacted with the NF-κB subunit p65 (RelA) and inhibited p65-driven gene expression." (PMID 36438567, 2022). "Although shRNA depletion of RelA in vivo was found not to affect progression of established lymphomas, it did result in resistance to cyclophosphamide treatment due to an impaired induction of cell senescence." (PMID 36240065, 2022). "To verify whether the XPO1E571K protein is fully functional, we analysed the localisations of two XPO1 cargoes known to be relevant for lymphoma pathology: nucleophosmin (NPM) and RELA." (PMID 33007990, 2020). "Further evidence that RelA T505A cells have fundamentally rewired their cell signalling pathways came from analysis of the intrinsic difference between Eμ-Myc WT and Eμ-Myc/RelaT505A lymphoma cells without CCT244747 treatment." (PMID 36240065, 2022). "To explore regulation of the proteome in WT and RelA T505A reimplanted lymphomas, with and without 8 h treatment with CCT244747, we used tandem mass tag (TMT)-based isobaric labelling to quantify relative changes in both total protein levels and phosphopeptide abundance." (PMID 36240065, 2022). "Similarly, our RNA Seq analysis of these samples confirmed a reduction in Clspn mRNA in c-Rel−/− lymphomas but again this was not the case with the RelA T505A Eμ-Myc lymphomas." (PMID 36240065, 2022).
colorectal cancer (11 papers, 2017 to 2026). A primary or metastatic malignant neoplasm that affects the colon or rectum. "More precisely, miR-221/222 have been documented to regulate NF-κB and STAT3 signaling by directly binding to the RelA mRNA coding region, increasing its stability and stimulating colorectal cancer (CRC) development and progression." (PMID 40089465, 2025). "RelA is up-regulated in colorectal cancer, where it seems to participate in tumor angiogenesis, but is has also been mentioned to be involved in other types of cancer as well." (PMID 37047552, 2023). "For instance, positive correlation of MIIP high expression with poor prognosis was observed in esophageal squamous cell carcinomas; and phosphorylation of MIIP at Ser303 by PKCε could enhance RelA transcriptional activity and thus promote metastasis of colorectal cancer." (PMID 36130933, 2022). "For RIG-I-like receptor signaling pathway in colorectal cancer, MAPK9, MAPK14, MAP3K7, and RELA were enriched in the pathway." (PMID 39211773, 2024). "This study also demonstrated that hub genes (IL1B, GSK3B, NOS3, RELA, and CDK4) were most likely to be involved in the effects of oxidative stress brought on by geniposide in the prevention of colorectal cancer." (PMID 37894904, 2023). "Our PPI network analysis results showed that IL1B, GSK3B, NOS3, RELA and CDK4 were related to oxidative stress induced by geniposide against colorectal cancer." (PMID 37894904, 2023).
multiple myeloma (11 papers, 2013 to 2025). "Another study reported that RELA promoted the progression of myeloma through transcriptional activation of PSMD14." (PMID 40066751, 2025). "For example, the transcription factor RELA activated PSMD14, resulting in a positive PSMD14/NSD2‐RELA feedback loop that promoted the occurrence of myeloma." (PMID 40066751, 2025). "Nevertheless, not only mutations onto the non-canonical NF-κB module are prevalent in MM, but RelB NF-κB dimers also appear to supplement pathological RelA functions in myeloma cells." (PMID 29772694, 2018). "They mediate the expression of pro-survival genes, which are traditionally thought to be RelA targets, and supplement the anti-apoptotic RelA function by protecting myeloma cells from apoptotic, chemotherapeutic drugs." (PMID 29772694, 2018). "Multiple myeloma is a well-known hematologic malignancy that is regulated by Sp1 transactivation and the NF-κB pathway, and downregulation of Sp1 and RelA induces tumor regression." (PMID 27545642, 2016). "In line with this, depletion of either YY1 or RelA severely impaired MM tumor growth in xenograft models for human Myeloma in nude mice." (PMID 23874387, 2013). "The growth and survival of a subset of multiple myeloma depends on RelA alone, suggesting a RelA-mediated gene expression program could be critical for PC survival." (PMID 38169968, 2023). "Furthermore, chronic TNF treatment of these p100-depleted myeloma cells induced RelA:p50 as well as RelB:p50 complexes, both of which activated the expression of pro-survival factors." (PMID 31134075, 2019). "Intriguingly, pro-survival TNF response is attributed to RelB:p50, and not RelA:p50, NFκB activity in myeloma cells harboring non-canonical mutations." (PMID 27641334, 2017). "Moreover, depletion of either YY1 or RelA completely inhibited MM tumor growth in xenograft models for human myeloma." (PMID 23874387, 2013). "Moreover, it remains unclear if the myeloma-associated RelB only activates the expression of RelA-target pro-survival genes or also mediates the expression of genes that are normally not induced by RelA." (PMID 29772694, 2018). "In particular, NIK-dependent non-canonical signaling amplifies RelA NF-κB responses and canonical signaling reinforces RelB NF-κB activity in myeloma cells." (PMID 29772694, 2018). "Mutational activation of the non-canonical NFκB pathway modified TNF signaling to impart drug resistance in myeloma cells independent of the principal NFκB subunit RelA." (PMID 27641334, 2017). "In multiple myeloma, Bim transcription is repressed by the Yin Yang 1 (YY1)-RelA (p65) complex." (PMID 26405162, 2015). "RelA- and RelB-DNA binding activity in CD138+ cells from newly diagnosed multiple myeloma patients." (PMID 23555623, 2013).